CD163 (CD163 molecule)
Diseases named in the same sentence as CD163 in open-access papers (continued):
Sharing a sentence is not in itself a finding about the gene and the disease.
Lipedema (continued). "The results suggest that CD163 + macrophages are a crucial factor in lipedema and that repolarization of lipedema macrophages may normally differentiate adipose tissue-derived stem cells in vitro when assessed by cell lipid accumulation." (PMID 40419722, 2025). "The conditioned medium of the treated and untreated groups (from both lipedema and control patients) was used to differentiate adipose derived stem cells (ADSCs) and thus assess the potential contribution of the CD163+ cell population in inducing the formation of adipose tissue." (PMID 36605202, 2022). "Firstly, we could confirm our previous results by observing a significant 5-fold upregulation of CD163 in the lipedema SVF compared to the control SVF." (PMID 36605202, 2022). "In this study, we could show that SVF-conditioned medium from lipedema patients, where higher numbers of CD163+ cells were present, showed enhanced adipogenic differentiation." (PMID 36605202, 2022). "This hypothesis was further supported by RNA sequencing of macrophage marker CD11b-positive cells derived from adipose tissue of lipedema patients, identifying not only increased levels of CD163 but also elevated expression of other M2 macrophage markers such as CD301 and PPAR-γ coactivator 1-beta." (PMID 40149538, 2025). "Nevertheless, conditioned medium from lipedema SVFs (without treatment) showed a tendency towards a downregulation of the ATP-linked respiration, in line with previous results demonstrating a decrease of ATP-linked respiration due to CD163+ macrophages." (PMID 36605202, 2022). "Soluble CD163 is present in the bloodstream, and elevated sCD163 levels are found in the serum of critically ill patients as well as in chronic inflammatory and infectious conditions, which raised the possibility that sCD163 levels could serve as a tool to support the diagnosis of lipedema." (PMID 40149538, 2025). "The CyTOF analysis revealed that in lipedema, significantly more CD206+CD163+Clever-1+ immunosuppressive M2 macrophages were present, which further confirmed the increased CD163 expression previously observed in lipedema." (PMID 36605202, 2022). "We treated the SVF from 5 lipedema and 5 control with 100 nM IPI-549 in vitro and analyzed the expression of CD163, CD206 and CD68." (PMID 36605202, 2022). "Given the high CD163 levels on macrophages of subcutaneous fat tissues from lipedema patients, this suggests that this potential exosomal biomarker for lipedema does not contribute to the macrophage population found in the adipose tissue of these patients." (PMID 40149538, 2025). "Interestingly and in clear distinction to lipedema and secondary lymphedema, no increased immune cell infiltration was detected in lipohypertrophy, while the infiltration with CD4+, CD68+ or CD163+ cells was found comparable to the healthy controls." (PMID 37108757, 2023). "However, sCD163 levels in patients with lipedema were normal, suggesting that although high CD163 levels are commonly observed in adipose tissue and shedding of sCD163 is induced in inflammation, this may not occur in the adipose tissue of lipedema patients." (PMID 40149538, 2025).
prostate tumors (9 papers, 2019 to 2026). "Infiltrating CD163‐positive M2 macrophages at a high level in the prostate tumor environment increases risk of dying of PCa." (PMID 35517503, 2022). "Macrophages are the most abundant immune cell type found in prostate tumours and CD163+ macrophages are predictive of a poorer prognosis." (PMID 38448753, 2024). "Immunohistochemical analyses were performed to identify CD209+ (immature DC), CD83+ (mature DC), CD68+ (total MΦ) and CD163+ (M2-type MΦ) cells in the 99 prostate tumors." (PMID 37435060, 2023). "Macrophages are an important component of all prostate tumors; their presence is associated with cancer progression and clinical outcomes depending on their phenotype (either cytotoxic-M1 (CD68) or protumorigenic-M2 (CD163))." (PMID 37444476, 2023).
pulmonary TB (9 papers, 2011 to 2023). "This is further substantiated by the use of CD163 as a potential marker for pulmonary TB in humans, with increased levels of CD163 associated with higher rates of mortality in patients with active TB." (PMID 31121006, 2019). "Lung sections of patients with pulmonary tuberculosis (n = 13) were immunostained for TCRαβand the macrophage markers CD68 and CD163, respectively." (PMID 22114556, 2011).
synovial sarcoma (9 papers, 2014 to 2025). "As reported by Pillozzi and colleagues, low CD163+ levels are associated with favorable survival in synovial sarcoma, while high levels of CD163+ are associated with enhanced survival in embryonic rhabdomyosarcoma." (PMID 39195816, 2024). "At the same time, in in embryonic rhabdomyosarcoma high levels of CD163+ are positively associated with survival, while in synovial sarcoma low CD163+ levels are associated with longer survival." (PMID 37296922, 2023). "The most common phenotype is M2, and low CD163+ levels are associated with favorable survival in synovial sarcoma; in embryonic rhabdomyosarcoma, on the other hand, high levels of CD163+ are positively associated with survival." (PMID 34207243, 2021). "In synovial sarcoma, patients with higher CD8+ or FOXP3+ lymphocyte infiltration were associated with good overall survival, whereas patients with higher CD163+ macrophage infiltration had significantly lower overall and progression-free survival." (PMID 38240704, 2024). "When evaluating synovial sarcoma samples, the most prevalent immune marker was CD68/CD163." (PMID 35267598, 2022). "However, the number of CD163-positive macrophages and naphthol AS-D chloroacetate esterase-positive granulocytes were not different between synovial sarcoma with and without miR-214 expression." (PMID 32019274, 2020).
acute kidney injury (8 papers, 2012 to 2025). Sudden and sustained deterioration of the kidney function characterized by decreased glomerular filtration rate, increased serum creatinine or oliguria. "CD163+ macrophages can predict the patients with IgAN at high risk for worse renal outcomes with macroscopic hematuria-related acute kidney injury." (PMID 37529043, 2023). "A case study demonstrated that CD163 is abundantly expressed in acute kidney injury and the expression of CD163 has been shown to be upregulated in kidney tissue in acute crescentic glomerulonephritis." (PMID 40443963, 2025). "Hemolysis was described in patients following thermal injury, and the circumstance that hemolysis can lead to acute kidney failure makes CD163 an interesting marker for monitoring patients after ablative treatments." (PMID 36353535, 2022). "Conjugating anti-CD163 antibody to gold-coated iron oxide have been found advantageous in specific MRI detection of CD163+ macrophages in atherosclerotic lesions and rhabdomyolysis-induced acute kidney injury in mice models." (PMID 32752088, 2020). "Moreover, Gutiérrez and collaborators indicated that CD163 positive macrophages infiltration determine long-term renal outcome in macro hematuria-induced acute kidney injury of IgAN." (PMID 30022351, 2018).
Arthritis (8 papers, 2013 to 2025). Inflammation of a joint. "Further, the anti-inflammatory response to collagen-induced arthritis is hampered in CD163 deficient mice compared to CD163 expressing mice indicating a pivotal role of CD163 in limiting arthritis progression and regression." (PMID 32752088, 2020). "In terms of maximal clinical score, the severity of arthritis of the CD163 deficient mice was more than three-fold higher." (PMID 32710083, 2020). "In contrast, litter-mates deficient of CD163 expression (CD163 -/-) displayed a much more severe arthritis with early onset and much prolonged response (p < 0.0001)." (PMID 32710083, 2020). "We then explored if the increase in arthritis severity was caused by a CD163-dependent defect in the T cell compartment." (PMID 32710083, 2020). "Compared to wild-type mice, the CIA in CD163-deficient mice had a several-fold higher arthritis score with early onset, prolonged disease and strongly enhanced progression." (PMID 32710083, 2020). "However, the endocytosis of any of these ligands does not readily explain the strong effect on the change in Th1/Th2 balance and the increase in arthritis disease severity in the CD163-deficient mice in the present study." (PMID 32710083, 2020). "In the present study, we observed a much more severe development of CIA in C57BL/6 mice deficient in CD163 expression compared to wild-type C57BL/6 mice that have a genetic background characterized by a general low susceptibility to collagen immunization in terms of arthritis development." (PMID 32710083, 2020). "The presence of CD1c+CD14+CD163+ DC3s in SF from patients with arthritis aligns with the reports of CD163+ DC3s detected in SF and tissue in OA, and CD1c+CD14+ DCs described in inflammatory tumor ascites and RA SF." (PMID 40687784, 2025). "CD163 deficient mice have shown a hindered anti-inflammatory response during the course of collagen-induced arthritis, as compared to wild type mice, indicating the pivotal role of CD163 and CD163+ macrophages in limiting arthritis progression." (PMID 35741108, 2022). "It is possible that the anti-inflammatory effect of CD163 in arthritis as well as the changed Th1/Th2 balance relates to the function of CD163 as an endocytic receptor in the macrophages." (PMID 32710083, 2020). "In the present study, we have observed and described profound effects on the Th1/Th2 balance and arthritis severity in collagen-immunized C57/BL6 mice, when M2 macrophages become deficient of one of their major plasma membrane components, the receptor CD163." (PMID 32710083, 2020). "Several cytokine and chemokines genes involved in the inflammatory signaling cascade during development of human arthritis were up- or down-regulated in CD163−/− mice compared to the wildtype mice." (PMID 32710083, 2020). "GM-CSF is highly expressed by sublining CD90+ FAP+ synovial fibroblasts, CD90+ activated endothelium and CD163+ macrophages in different types of arthritis." (PMID 33679701, 2020). "CD163-expressing macrophages have been detected at sites of inflammation, such as chronically inflamed arthritis-affected joints and in the vicinity of tumor cells (tumor-associated macrophages), in particular in CCA associated with O. viverrini infection." (PMID 31086416, 2019). "Therefore, the expression of activin A, MMP12 and TNFα designates the GM-CSF-dependent pro-inflammatory state of CD163+ ST macrophages in undifferentiated and established arthritis." (PMID 33679701, 2020). "Furthermore, the present data provide a new model for studying experimental arthritis in gene knock-out models by breeding into CD163 knock-out mice or by inactivation of CD163 expression/function by other means (e.g. CRISP-Cas)." (PMID 32710083, 2020).
Arthritis (continued). "We also found that the ST sublining of undifferentiated and established arthritis patients showed a high percentage of CD163+ CD209low/- whereas healthy controls exhibited a high percentage of CD163+ CD209+, suggesting they may be resident macrophages with a potential anti-inflammatory function." (PMID 33679701, 2020). "In the present study, Lip-PLP caused an upregulation of CD163 in bone marrow macrophages which was also found to be upregulated in the synovium at day 1 after treatment of experimental arthritis models ICA and AIA (although not statistically significant in the latter)." (PMID 23468840, 2013). "Expression of CD64 and CD163 on monocytes and PDL2, CD86, and HLA-DR on DC discriminate both type of arthritis." (PMID 32849606, 2020). "Less difference in disease severity between the CD163+/+ and CD163−/− mice was seen in the CAIA model that to a large extent induces arthritis independently of T-cell response and endogenous Th1/Th2 balance." (PMID 32710083, 2020). "CD163+ macrophages expressed a pro-inflammatory profile of biomarkers (activin A, TNFα, and MMP-12) in synovial tissue from all arthritis subtypes studied, while in paired samples of synovial fluid only activin A levels were widely detected." (PMID 33679701, 2020). "Surprisingly, the enhanced arthritis disease in the CD163−/− mice was not accompanied by an apparent increased Th17 response." (PMID 32710083, 2020). "The majority of M2 markers (IL-1RII, CD163, CD206, Arg1 and Ym1) were also somewhat upregulated during the course of arthritis, although in lesser extent than the M1 markers, with the exception of Arg1 and Ym1 which were especially high at day 1 after induction of AIA." (PMID 23468840, 2013).
chronic obstructive pulmonary disease (8 papers, 2014 to 2025). A chronic and progressive lung disorder characterized by the loss of elasticity of the bronchial tree and the air sacs, destruction of the air sacs wall, thickening of the bronchial wall, and mucous accumulation in the bronchial tree. "For instance, CD163 has been confirmed to be overexpressed on alveolar macrophages in patients with severe chronic obstructive pulmonary disease." (PMID 38887981, 2024). "High CD163 expression on alveolar macrophages was reported in patients with chronic obstructive pulmonary disease (COPD) and in idiopathic pulmonary fibrosis." (PMID 33777012, 2021). "The numbers and percentages of M2 markers CD163+CD204+ alveolar macrophages were positively associated with the severity of chronic obstructive pulmonary disease (COPD), with higher numbers in smoker patients than non-smokers." (PMID 33763066, 2021). "Very recently, the surface expression of CD163 and S100A9 on classical monocytes has been associated with chronic obstructive pulmonary disease (COPD) and host background factors, such as age and smoking." (PMID 34108546, 2021). "For instance, the numbers and percentages of M2-polarized alveolar macrophages expressing markers CD163+, CD204+, and CD206+ increases with the severity of chronic obstructive pulmonary disease, with higher numbers in smoker patients than non-smokers." (PMID 33763066, 2021).
endothelial dysfunction (8 papers, 2012 to 2025). In vascular diseases, endothelial dysfunction is a systemic pathological state of the endothelium (the inner lining of blood vessels) and can be broadly defined as an imbalance between vasodilating and vasoconstricting substances produced by (or acting on) the endothelium. "CD163, the main hemoglobin-haptoglobin receptor expressed on monocytes/macrophages, plays an important role in the clearance of hemoglobin and its determination may be useful to better understand hemolysis-related endothelial dysfunction." (PMID 36699704, 2022).
IgA nephropathy (8 papers, 2013 to 2025). "Our observation that CD163+ macrophage infiltration was associated with decreased renal function was confirmed for other renal disease like IgA-nephropathy and in patients after kidney transplantation." (PMID 27091114, 2016). "In addition, CD163, a marker for M2 macrophage polarization associated with IgA nephropathy in adults, was highly upregulated and negatively correlated with renal function." (PMID 25133636, 2014). "It is also reported that CD163 was expressed in several kidney diseases related to the accumulation of hemoglobin in renal tissue, such as IgA nephropathy, macroscopic hematuria with AKI, paroxysmal nocturnal hemoglobinuria, and warm antibody hemolytic anemia." (PMID 39949667, 2025). "CD163-expressing macrophages are also overrepresented in the colon of patients with diverticulitis and in the kidney of patients with IgA nephropathy." (PMID 23922818, 2013). "In macrophages of patients with IgA nephropathy and macroscopic hematuria-related AKI, CD163 was associated with incomplete recovery of kidney function describing as the predominant subpopulations in kidney tissues, the M2a (CD206+/CD68+) and M2b (CD86+/CD68+) macrophages." (PMID 34307414, 2021).
leukemia (8 papers, 2020 to 2025). A malignant (clonal) hematologic disorder, involving hematopoietic stem cells and characterized by the presence of primitive or atypical myeloid or lymphoid cells in the bone marrow and the blood. "We found that inhibition of MerTK decreased leukemia-associated macrophage expression of M2 markers PD-L1, PD-L2, Tim-3, CD163 and Arginase-1 compared to vehicle-treated controls." (PMID 36960055, 2023). "We established the indirect coculture system (intraepithelial neoplasia model) and direct coculture system (invasive cancer model) of human monocytic leukemia cell line THP-1-derived CD163-positive macrophages with SCC25, a tongue squamous cell carcinoma (TSCC) cell line." (PMID 34178651, 2021). "Targeting efferocytic macrophages within the spleen and marrow leukemia microenvironments, we demonstrated that MRX2843 decreased macrophage immunosuppressive features including a reduction in M2-like markers PD-L1, PD-L2, Tim-3, CD163, and Arginase-1." (PMID 36960055, 2023). "Moreover, p21 was unlikely to be involved in the proinflammatory reprogramming of MDMs following leukemia cell engulfment, since p21 overexpression and p21 knockdown failed to modulate the expression of CD163 and IRF5, respectively." (PMID 36347876, 2022).
metastasis (8 papers, 2019 to 2024). The spread or migration of cancer cells from one part of the body (where they first appeared) to another. "In invasive tumours, microvessel density is significantly correlated with CD163‐positive macrophages and lymph node metastasis in the corresponding region." (PMID 33439514, 2021). "In addition, high infiltration of M2-polarized (CD206+ and CD163+) TAMs was correlated with larger tumour size, lymph node metastasis, and more advanced clinical stage of BMC." (PMID 39073672, 2024). "Correlation between clinical characteristics and status of CD68, CD163, and SOCS3 in lung metastasis." (PMID 37025997, 2023). "According to our meta-analysis results, we found that a high density of both CD68- and CD163-positive macrophages was significantly associated with high Ki67 expression, advanced histological stage, low HR expression and short OS, but not with tumor size, lymph node metastasis and HER2 expression." (PMID 31528210, 2019).
metastatic melanoma (8 papers, 2018 to 2024). A melanoma that has spread from its primary site to another anatomic site. "Here we initially sought to examine the origin of CD163+ TAMs accumulated in human metastatic melanoma." (PMID 38903497, 2024). "While their frequencies varied between samples, proliferating CD163+ TAMs were found in most of the metastatic melanoma samples we examined." (PMID 38903497, 2024). "Our data demonstrated that CD163+ TAMs accumulated in human metastatic melanoma display molecular phenotypes that strongly suggest they are derived from CD14+ CCR2+ monocytes." (PMID 38903497, 2024). "As previously reported, in metastatic melanoma, a substantial number of CD163+ TAMs are present in metastatic melanoma and are activated by stromal factors, leading to an increase in serum levels of sCD163 as a result of proteolytic shedding." (PMID 30510916, 2018). "Regarding CD163, a recent study reported that the activation of effector T cells and the depletion of macrophages 163+ in the tumour are associated with a good response to BRAF inhibitor treatment in patients with metastatic melanoma." (PMID 35203494, 2022).